SNORD115-19 (small nucleolar RNA, C/D box 115-19)
Synonyms: HBII-52-19
Gene: Small nucleolar RNA gene on chromosome 15 (25,204,357 to 25,204,438, forward strand). Ensembl gene ENSG00000199968.
Gene Ontology:
Biological process: RNA processing
Cellular component: nucleolus
Homologues: Orthologues: macaque SNORD115 (96% identical). Paralogues in human: SNORD115-17 (100% identical), SNORD115-18 (100% identical), SNORD115-20 (98% identical), SNORD115-12 (96% identical), SNORD115-9 (96% identical), SNORD115-10 (95% identical), SNORD115-11 (95% identical), SNORD115-13 (95% identical), SNORD115-29 (95% identical), SNORD115-36 (95% identical), SNORD115-40 (95% identical), SNORD115-42 (95% identical), and 37 more.